CRP (C-reactive protein)
Diseases named in the same sentence as CRP in open-access papers (continued):
Sharing a sentence is not in itself a finding about the gene and the disease.
Granuloma (9 papers, 2012 to 2025). A compact, organized collection of mature mononuclear phagocytes, which may be but is not necessarily accompanied by accessory features such as necrosis. "Patients of TS frequently presented more granuloma, caseous necrosis, epithelial-like reaction, interleukin 6 (IL-6), and C-reactive protein (CRP) than those of BS." (PMID 33959835, 2021). "Fucoidan from the brown algae Turbinaria ornata reduced the levels of inflammatory biochemical markers in cotton-pellet induced granulomas in rats, such as cathepsin D, myeloperoxidase (MPO) and C-reactive protein (CRP), somewhat comparable to dexamethasone." (PMID 38132941, 2023). "The inflammatory status as assessed by the CRP level was not significantly different in infected patients who did or did not form granulomas." (PMID 32411623, 2020). "In immunocompromized hosts with low CRP levels, granuloma lesions and cavitation might not develop even under severe disease conditions." (PMID 31344108, 2019).
Hematochezia (9 papers, 2021 to 2025). The passage of fresh (red) blood per anus, usually in or with stools. "The patient had persistent fever and elevated CRP, but the hematochezia, abdominal pain, and inflammatory markers gradually improved." (PMID 41497709, 2025). "At admission, AMI patients were also more likely to present with sudden-onset and/or morphine-requiring abdominal pain, hematochezia, guarding, organ dysfunction, higher white blood cell and neutrophil counts, and CRP and plasma procalcitonin concentrations." (PMID 37287011, 2023). "Overall, 58.3% of participants treated with tofacitinib 10mg twice daily responded by day 7, and in some cases improvement of clinical and biochemical parameters, including diarrhea, hematochezia, and CRP was observed as early as 2 days after tofacitinib initiation." (PMID 40092634, 2025). "Initial lab results included hemoglobin of 6.1 g/dl, normal CRP, and positive stool tests, without hematochezia." (PMID 40611925, 2025). "Patients with no improvement or with exacerbations in diarrhea, hematochezia, and UC-related laboratory indicators (e.g., C-reactive protein, white blood cell count, hemoglobin) after single FMT (Step 1) were considered for the “step-up FMT strategy” described in our previous study." (PMID 37571277, 2023).
hemoglobinopathies (9 papers, 2006 to 2026). "During the initial evaluation, each patient was assessed for complete blood count, iron metabolism, B12, folates, hemoglobinopathies, CRP, kidney and liver function, and glucose levels." (PMID 41562674, 2026). "Hematological and biochemical assessments included serum ferritin, iron, C-Reactive Protein (CRP), folate, vitamin B12, prealbumin, and hemoglobinopathy screening." (PMID 41458907, 2025). "Blood samples were collected before and after intervention for haemoglobin, serum ferritin (SF), serum transferrin receptor (TfR), C-reactive protein (CRP), and haemoglobinopathies analysis." (PMID 17147795, 2006). "We did not test for haemoglobinopathies or measure C-reactive protein in this population, however previous studies have shown that hemoglobinopathies are not highly prevalent in the Kinh population in Vietnam, and are more commonly seen in ethnic minority groups." (PMID 35164876, 2022).
Hernia (9 papers, 2019 to 2025). "Longer time interval from emergence visit to laparotomy (p = 0.042) and elevated preoperative procalcitonin (p = 0.033) and C-reactive protein (CRP; p = 0.012) were associated with higher risk of bowel necrosis in Petersen’s hernia." (PMID 34820331, 2021). "Hernia surgery was shown to increase CRP, IL-6 levels, leukocyte count, neutrophil count, IL-1 levels, IL-10 levels, fibrinogen, and α1-antitrypsin, and decrease lymphocyte counts and albumin during the first 24 postoperative hours." (PMID 36739352, 2023). "In this study, the ability of the CRP level to predict postoperative complications after incisional hernia repair surgery using a biological mesh was investigated." (PMID 33623063, 2021). "Higher peripheral blood leucocytes and serum C-reactive protein values prior to hernia repair might be an expression of the emergency character due to bowel incarceration in the group of patients, who underwent surgery without mesh implantation." (PMID 33713205, 2022). "This retrospective study assessed whether the postoperative C-reactive protein (CRP) level can predict complications after incisional hernia repair using biological mesh reinforcement." (PMID 33623063, 2021). "Prognostic indicators containing objective measures of inflammatory and immune responses, that is, lymphopenia and significantly raised CRP and declined albumin, could foresee strangulation and requirement of resection in the patient with incarcerated abdominal hernias." (PMID 40389774, 2025). "By evaluating CRP as an inflammation marker and albumin as a negative acute-phase protein, we hypothesized that PNI will be a major factor in the prognosis of strangulation and resection in abdominal hernia patients with incarceration." (PMID 40389774, 2025).
Hydrocephalus (9 papers, 2016 to 2026). Hydrocephalus is an active distension of the ventricular system of the brain resulting from inadequate passage of CSF from its point of production within the cerebral ventricles to its point of absorption into the systemic circulation. "The optimal cut-off values of “age,” “Hunt-Hess grade,” “CRP” and “neutrophil” were 61.5, 3.5, 11.4, and 9.06, respectively, in predicting the poor prognosis of aSAH combined with hydrocephalus at 6 months after surgery." (PMID 36353134, 2022). "The AUC of CRP, neutrophil, age and Hunt-Hess grade for predicting poor prognosis in patients with aSAH combined with hydrocephalus at 6 months after surgery were 0.804, 0.735, 0.596, 0.757, respectively." (PMID 36353134, 2022). "“CRP,” “neutrophil,” “age” and “Hunt-Hess grade” at admission are independent predictors of clinical prognosis in patients with aSAH complicated with hydrocephalus." (PMID 36353134, 2022). "The detection of CRP and neutrophil levels in aSAH patients with hydrocephalus on admission combined with Hunt-Hess grading scale can identify high-risk groups with poor prognosis and provide early intervention." (PMID 36353134, 2022). "Statistically significant changes from the baseline to the time of development of paradoxical reaction was observed in fever, headache, hydrocephalus, tuberculoma, c-reactive protein, erythrocyte sedimentation rate, and cerebrospinal fluid polymorphs, lymphocytes, and protein." (PMID 27329253, 2016). "We identified significant increases in vascular injury proteins (CRP, SAA, ICAM-1, and VCAM-1) at 5 days post-injury in the serum and CSF when compared to healthy, age-matched and unaffected (hydrocephalus) controls, respectively." (PMID 40427506, 2025).
hyperparathyroidism (9 papers, 2014 to 2025). Hyperfunction of the parathyroid glands resulting in the overproduction of parathyroid hormone. "Some showed elevated levels of these inflammatory markers in hyperparathyroidism, whereas others found that levels of CRP, IL-6, and leukocytes were similar in patients and controls." (PMID 24782595, 2014). "In this context, patients with hyperparathyroidism will, theoretically, have higher levels of IL-6, CRP, or tumor necrosis factor-α (TNF-α)." (PMID 24782595, 2014). "Other studies showed elevated levels of C-reactive protein (CRP), tumor necrosis factor-a and other inflammatory markers in hyperparathyroidism patients." (PMID 33312065, 2020). "Aged 17 years or older, receiving dialysis for 4 h, three times a week; positive C-reactive protein (CRP) result; no severe hyperparathyroidism; no active bleeding or surgery in the past 3 months; no hemoglobin (Hb) disorders." (PMID 40735439, 2025). "While biochemical markers like CRP, urea, and creatinine were measured, other potential confounding factors, such as genetic influences, other medications, or comorbid conditions like hyperparathyroidism, were not fully accounted for." (PMID 40265109, 2025).
hypersomnia (9 papers, 2019 to 2024). A sleep disorder characterized by excessive sleepiness. "In particular, both higher CRP and IL-6 showed converging associations with hypersomnia (CRP OR = 1.27, 95% CI = 1.13–1.43; IL-6 OR = 1.26, 95% CI = 1.07–1.49) and fatigue (CRP OR = 1.12, 95% CI = 1.04–1.21; IL-6 OR = 1.19, 95% CI = 1.07–1.33)." (PMID 34135474, 2021). "Large-scale genomic studies identified shared genetic liabilities between symptoms of hyperphagia, hypersomnia and weight gain during a depressive episode and traits such as elevated CRP, leptin, and body mass index (BMI), partially explaining their phenotypic connection." (PMID 37301859, 2023). "Only hypersomnia, but not loss of sleep, showed consistent associations with CRP and IL-6." (PMID 34135474, 2021). "Findings of increased CRP levels and IL-6 overactivity with other PHQ-9 symptoms were inconsistent, but there were some indications that IL-6 signaling could be associated with hypersomnia, which requires replication in future work." (PMID 33079133, 2021).
hypovitaminosis (9 papers, 2015 to 2023). "Among the quintiles of plasma vitamin C considered insufficient (deficiency, hypovitaminosis, and inadequate) mean CRP levels ranged from 0.53 mg/dL (95% CI: 0.50–0.57) to 0.67 mg/dL (95% CI: 0.54–0.80)." (PMID 35334908, 2022). "Multiple regressions explored both associations of CRP with other inflammatory markers and associations of CRP and elevated CRP based on trimester-specific cut-offs with maternal factors, infections and vitamin deficiencies." (PMID 28571565, 2017). "Specifically, they had normal serum concentrations of folate (>5 ng/mL), vitamin B-12 (>200 pg/mL) and C-reactive protein (CRP) (<10 mg/L), excluding possible influences on Fe status from vitamin deficiency and inflammation." (PMID 26054392, 2015). "The usefulness of C-reactive protein (CRP) as a non-specific marker of inflammation during pregnancy and lactation is unclear in impoverished populations where co-existing infections and vitamin deficiencies are common." (PMID 28571565, 2017). "In addition to serum Hcy, erythrocyte sedimentation rate (ESR), C-reactive protein (CRP) and bone turnover markers (bone alkaline phosphatase-BAP, osteocalcin-OC, C-terminal telopeptide of type I collagen (CTX), vitamin deficiencies and MTHFR-C677T polymorphism were evaluated." (PMID 32549258, 2020). "Treatment of hypovitaminosis has been shown to decrease SOFA scores, PCT, C-reactive protein, and thrombomodulin levels, which can translate to decreases in organ failure, inflammation, and endothelial injury." (PMID 30970560, 2019).
hypoxic-ischemic encephalopathy (9 papers, 2015 to 2025). "Prolonged sleep deprivation also induces inflammatory activation—elevated TNF-α and C-reactive protein have been observed in women with perinatal depression, particularly among those with trauma histories." (PMID 41561847, 2025). "It has been shown that the CRP level is high in cases diagnosed wit hypoxic ischemic encephalopathy and undergoing hypothermia treatment." (PMID 37684308, 2023). "A case with acute encephalopathy as the initial presentation of CADASIL was reported with a CRP of 23 mg/L, while a study on newborns diagnosed with hypoxic-ischemic encephalopathy reported median a CRP of 15.4mg/L." (PMID 37873776, 2023). "Further investigation of IL-8 and CRP in relation to treatment response, along with replication of TNF-α findings, is warranted to advance perinatal depression research." (PMID 41440970, 2025). "Out of 303 patients with SE, 58 patients with hypoxic-ischemic encephalopathy and 154 patients without measurements of acute-phase proteins (i.e., serum levels of PCT, CRP and albumin) within the first 24 hours after SE onset were excluded." (PMID 26450065, 2015).
intrahepatic cholangiocarcinoma (9 papers, 2015 to 2025). A carcinoma that arises from the intrahepatic bile duct epithelium in any site of the intrahepatic biliary tree. "We confirmed a significant association of elevated pre-operative CRP levels with poor clinical outcomes for the tested patients with intrahepatic cholangiocarcinoma." (PMID 27733196, 2016). "CRP has been reported as a predictor of prognosis in patients with intrahepatic cholangiocarcinoma treated with anti‐PD‐1 therapy." (PMID 37930138, 2023). "In patients with stage I/II intrahepatic cholangiocarcinoma, the serum CRP level was a prognostic indicator for cancer-specific survival." (PMID 27733196, 2016). "We sampled the CRP levels in 140 patients with intrahepatic cholangiocarcinoma who underwent hepatectomies with regional lymphadenectomies between 2006 and 2013." (PMID 27733196, 2016). "Additionally, multivariate analysis identified serum CRP level in intrahepatic cholangiocarcinoma as an independent prognostic factor (P < 0.05)." (PMID 27733196, 2016). "However, the prognostic significance of CRP levels collected before tumor removal in intrahepatic cholangiocarcinoma requires further investigation." (PMID 27733196, 2016). "Our results indicate that the serum CRP level may represent a useful factor for patient stratification in intrahepatic cholangiocarcinoma management." (PMID 27733196, 2016). "The aim of this study is to explore the prognostic value of CRP–Albumin–Lymphocyte (CALLY) index in patients undergoing radical resection of intrahepatic cholangiocarcinoma (ICC)." (PMID 40115790, 2025). "The present study aimed to investigate the impact of preoperative C-reactive protein to albumin (CRP/Alb) ratio on the long-term outcomes of patients with intrahepatic cholangiocarcinoma (ICC)." (PMID 32856868, 2020). "ECC: extrahepatic cholangiocarcinoma; ICC: intrahepatic cholangiocarcinoma; ALT: alanine aminotransferase; AST: aspartate aminotransferase; AP: alkaline phosphatase; GGT: gamma-glutamyl transferase; CRP: C-reactive protein; WBC: white blood cells; CA 19–9: carbohydrate antigen 19–9." (PMID 26431155, 2015).
laryngeal carcinoma (9 papers, 2019 to 2026). Carcinoma that arises from the laryngeal epithelium. "Contemporary evidence has confirmed that HNF1A binds to the promoter region of CRP, thereby upregulating CRP expression and promoting laryngeal cancer progression." (PMID 41583511, 2026). "Fu and Yang22 demonstrated that the CRP/PNI is a prognostic indicator in patients with laryngeal cancer." (PMID 38376000, 2024). "The aim of this study was to assess the correlation between biomarkers of oxidative stress (MDA, SOD, and GPX) and inflammation (IL-1, IL-6, CRP) and postoperative pain management in surgically treated patients with laryngeal cancer." (PMID 37408225, 2023). "More recently, pre-therapeutic indices of systemic inflammation based on CRP and albumin have been found to provide prognostic information in nasopharyngeal and laryngeal cancer patients." (PMID 32182693, 2020). "High expression of CRP indicates a poor outcome in patients with malignant tumors, including laryngeal cancer." (PMID 31312573, 2019). "In this research, we showed that the CRP/PNI ratio was a predictor of advanced laryngeal cancer patients." (PMID 31312573, 2019). "In summary, our study identified a CRP/PNI ratio of >0.10 to be a signature indicator for the outcomes of advanced laryngeal cancer." (PMID 31312573, 2019). "The CRP/albumin ratio could predict poor survival in patients with hypopharyngeal and laryngeal cancer." (PMID 35847918, 2022). "CRP/PNI may be used as a prognostic indicator for laryngeal cancer patients treated with radiotherapy." (PMID 31312573, 2019). "The data show that CRP/PNI may be used as a prognostic indicator for laryngeal cancer patients treated with radiotherapy." (PMID 31312573, 2019). "Thus, in the present research, we first studied the importance of CRP/PNI in evaluating the prognosis of laryngeal cancer patients." (PMID 31312573, 2019). "It is stated that the C-reactive protein/albumin ratio (CAR) is a new independent prognostic factor for total survival and disease-free survival in laryngeal cancer." (PMID 37081512, 2023). "The object of this research was to evaluate the significance of CRP/PNI and survival in laryngeal cancer patients." (PMID 31312573, 2019). "The potential role of the CRP/PNI ratio and other indicators in laryngeal cancer remains to be investigated at a broader and deeper level." (PMID 31312573, 2019). "However, there has been no research that has shown the relationship between the prognostic value of CRP/PNI and laryngeal cancer." (PMID 31312573, 2019). "Moreover, pre-treatment elevated CRP predicts a poor prognosis in cases with locoregionally advanced laryngeal carcinoma treated with chemoradiotherapy, yet another study found that the overall survival was independent of serum CRP levels." (PMID 37873776, 2023).
lung squamous cell carcinoma (9 papers, 2012 to 2025). "Nonlinear relationship analysis revealed that age (particularly > 66 years) and moderate inflammatory status (CRP 20–30 mg/L) are key features of increased squamous cell lung cancer risk, providing reference for identifying high-risk RA patients." (PMID 41327467, 2025). "The highest risk was seen in squamous cell lung cancer, where CRP levels were elevated up to 5 years before cancer diagnosis and risk of cancer rose steadily with increasing CRP levels." (PMID 39309742, 2024). "Notably, metabolic abnormalities (TG, blood glucose) and systemic inflammation (ESR, CRP) are the most important predictive factors, which is consistent with clinical association analysis, providing clues for understanding the biological mechanisms of RA-squamous cell lung cancer association." (PMID 41327467, 2025). "Also other study groups found the predictive value of baseline CRP levels on the efficacy of chemotherapy plus immune checkpoint inhibitors in patients with advanced lung squamous cell carcinoma." (PMID 38877146, 2024). "In the Rotterdam Study, CRP was associated with a increased risk of lung squamous cell carcinoma, but not adenocarcinoma." (PMID 22912790, 2012).
memory impairment (9 papers, 2015 to 2025). "Noble, Manly reported that the elderly with higher C-reactive protein levels are at a higher risk of memory impairment." (PMID 36798738, 2023). "Specifically, animals exposed prenatally had elevated C-reactive protein levels, decreased plasma cortisol levels, and more passive behavior and memory impairment." (PMID 36548583, 2022). "Higher CRP levels were associated with MCR with memory impairment but not with MCR without memory impairment." (PMID 38337499, 2024). "In another study with 421 participants, where CRP was related to motor cognitive risk syndrome (MCR), characterized by cognitive complaints and slow gait, patients with higher CRP levels (2.8 mg/dL) had a higher probability of MCR if memory impairment was present." (PMID 38338653, 2024). "CRP may serve as a marker for memory impairment and visuospatial dysfunction in the elderly." (PMID 39114530, 2024).